IDH1 (isocitrate dehydrogenase (NADP(+)) 1)
Diseases named in the same sentence as IDH1 in open-access papers (continued):
Sharing a sentence is not in itself a finding about the gene and the disease.
oligodendroglioma (continued). "Following resection, the lesion was diagnosed histopathologically as a 1p/19q co-deleted anaplastic oligodendroglioma although it was noted that the IDH1 (R132H) antibody (IHC) was negative." (PMID 31806041, 2019). "Similar to previously reported pediatric oligodendrogliomas, this congenital tumor was negative for 1p/19q codeletion as well as for R132H mutant specific IDH1 by immunohistochemistry." (PMID 25755903, 2015). "We were unable to compare IDH1 R132H mutant and IDH1-immunonegative tumors in oligodendroglioma because only one tumor in our cohort was negative for the IDH1 R132H mutation by immunohistochemistry." (PMID 22829908, 2012). "Therefore, H3K27me3 immunostaining can be regarded as a sensitive and specific molecular surrogate for defining IDH1-R132H Mut 1p/19q codeleted oligodendroglioma in the absence of molecular testing." (PMID 34020723, 2021). "We compared immunostaining with DNA sequencing and fluorescent in situ hybridization analysis and assessed differences in H3K27me3 staining between oligodendroglial and astrocytic lineages and between IDH1-R132H and non-canonical (non-R132H) IDH1/2 Mut oligodendroglioma." (PMID 34020723, 2021). "Thus, further investigations of the differential expression of H3K27me3 between IDH1-R132H and non-canonical IDH1/2 mutant oligodendrogliomas are required for prognostic and therapeutic application." (PMID 34020723, 2021). "Interestingly, in non-canonical IDH1-mutated (IDH1-R132L) or IDH2-mutated (IDH2-R172K, IDH2-R172W, IDH2-R172S) oligodendrogliomas with 1p/19q codeletion, loss of H3K27me3 was never observed." (PMID 34020723, 2021). "In contrast, neoangiogenesis was not apparent in an IDH1 mutant oligodendroglioma specimen." (PMID 30686972, 2018). "Four oligodendrogliomas with 1p/19q codeletion and typical oligodendroglial histology were designated to NOS group since IDH1/IDH2 mutation could not be detected." (PMID 28467778, 2017). "Four oligodendrogliomas in our cohort with 1p/19q codeletion and typical oligodendroglial histology were designated to NOS group since no IDH1/IDH2 mutation could be detected." (PMID 28467778, 2017). "However, H3K27me3 staining was always present in non-canonical IDH1/IDH2 Mut oligodendrogliomas." (PMID 34020723, 2021). "To determine this, we overexpressed IDH1-WT or one of five glioma-derived IDH1 R132 mutants with C-terminal MYC and FLAG tags in human oligodendroglioma (HOG) cells, a human glioma cell line that does not contain IDH mutations." (PMID 21326614, 2011).
chondrosarcoma (171 papers, 2012 to 2025). A malignant cartilaginous matrix-producing mesenchymal neoplasm arising from the bone and soft tissue. "A phase I/expansion study conducted in 2020 enrolled 21 patients with advanced chondrosarcoma harboring IDH1 mutations." (PMID 41357670, 2025). "In chondrosarcoma, the evidence that IDH1 mutations are initiating events is supported by a causative relationship with the early postzygotic conditions, Ollier disease and Maffucci syndrome, and by mouse models." (PMID 41299743, 2025). "To gain a deeper understanding of the role of IDH1/2 in chondrosarcoma metastasis, we performed detailed genomic profiling of metastatic central chondrosarcoma, with a specific focus on IDH1 and IDH2 mutations." (PMID 41299743, 2025). "Isocitrate dehydrogenase 1 (IDH1) mutations, which lead to the accumulation of the oncometabolite 2‐hydroxyglutarate (2‐HG), are frequently observed in chondrosarcoma, particularly in the conventional (diffuse‐type) subtype." (PMID 41357670, 2025). "Of note, although HT-1080 was originally isolated from connective tissue as an STS model, it was recently reclassified as a dedifferentiated chondrosarcoma line due to characteristic IDH1 mutation." (PMID 40075728, 2025). "In another study, the same group used the ddPCR assay to analyse ctDNA in pre- and postoperative blood samples of 83 chondrosarcoma patients with known IDH1/2 or GNAS hotspot mutations." (PMID 39797974, 2025). "Mutations in IDH1/2 contribute to increased DNA and histone methylation in chondrosarcoma (CS), although the resulting epigenetic landscape varies by subtype." (PMID 40867318, 2025). "No mutations were detected by pyrosequencing at codon 132 of IDH1 or codon 172 of IDH2 on genomic DNA extracted from the chondrosarcoma tumor." (PMID 38236556, 2024). "The IDH1 mutations were detected in 34/64 (53%) chondrosarcomas; IHC detected 27/56 (48.2%) mutations, the qPCR-DMA-Sanger method 27/59 (46%) mutations, and the biochip assay revealed 29/60 (48.3%) mutations." (PMID 38248076, 2024). "In general, the frequency of IDH1 mutation in head chondrosarcomas can vary from 0% to 85% depending on the localization, histological type, and stage." (PMID 38248076, 2024). "All patients with Grade 3 chondrosarcomas and dedifferentiated chondrosarcomas had IDH1/2 mutations." (PMID 38170705, 2024). "Patients with Grade 2 chondrosarcoma had lower 2-year overall survival if they also presented with the IDH1 R132 mutation than those with the wild-type gene or other mutations (75% [95% CI 45% to 100%] versus 100% [95% CI 100% to 100%]; p = 0.04)." (PMID 38170705, 2024). "Mutations in IDH1/2 genes serve as important diagnostic markers of tumor type, particularly chondrosarcoma." (PMID 38248076, 2024). "Four patients with Grade 1 chondrosarcomas had IDH1/2 mutations, whereas nine patients with Grade 2 chondrosarcomas had IDH1 mutations." (PMID 38170705, 2024). "The IDH1 mutations have been found predominantly in intracranial chondrosarcomas, as well as in chondromas affecting mainly the base of the skull." (PMID 38248076, 2024). "The frequency of IDH1 mutations in chondrosarcomas detected by all three methods was 45%, increasing to 53% when a positive result obtained by at least one method was considered." (PMID 38248076, 2024). "Preclinical data shows that ivosidenib inhibits invasion and migration of IDH1 mutated chondrosarcoma cell lines." (PMID 39876890, 2024). "Concerning chondrosarcoma, a clinical study showed that Olaparib was efficient for the treatment of IDH1/2 mutated chondrosarcomas." (PMID 39334838, 2024). "This is commensurate with the literature, as it is known that chondrosarcomas are affected more often by IDH1 mutations than IDH2." (PMID 38254737, 2024). "In chondrosarcomas, mutations in the IDH1 gene were detected at least by one method in 34/64 (53%) samples." (PMID 38248076, 2024).
chondrosarcoma (continued). "IDH1/2 mutations, found in approximately 39% of chondrosarcoma cases, are strongly correlated with poor survival, larger tumor size, higher grade, and increased relapse risk, positioning them as crucial prognostic indicators." (PMID 39590345, 2024). "There are few available studies on the frequency of IDH1/2 mutations in cartilage tumors of this rare localization, and they mainly concern chondrosarcomas." (PMID 38248076, 2024). "Differential methylation analysis revealed reduction of IDH1/IDH2-associated global hypermethylation characteristically seen in conventional chondrosarcoma and a distinct methylation profile in DDCS." (PMID 36926116, 2023). "IDH1 is most frequently mutated in chondrosarcoma and cholangiocarcinoma, specifically in the variant R132C." (PMID 37296846, 2023). "Isocitrate dehydrogenase 1/isocitrate dehydrogenase 2 (IDH1/IDH2) mutations were present in 36% conventional chondrosarcomas and 71% DDCS." (PMID 36926116, 2023). "Most importantly, a differential analysis of methylation patterns revealed a decrease in the global hypermethylation typically associated with IDH1/IDH2 in conventional chondrosarcoma." (PMID 37568740, 2023). "The IDH1/2 mutations are very interesting in sarcomas since they are a hallmark of chondrosarcomas and negatively impact overall survival." (PMID 37720343, 2023). "A small Olaparib combination phase II open-label study in which patients with solid tumors harboring IDH1/2 mutations were treated with Olaparib as monotherapy revealed that three of five patients with chondrosarcomas had clinical benefit." (PMID 36768638, 2023). "A recent clinical trial included five patients who had chondrosarcoma with tumors harboring IDH1/2 mutations; preliminary activity of PARP inhibition was observed." (PMID 36729612, 2023). "Consistently, we found the expression of angiogenic markers, VEGFA and CD31, was significantly reduced in the IDH1mut KO cell-derived tumors, suggesting that IDH1 mutation is associated with the angiogenic potential of chondrosarcoma cells." (PMID 35198082, 2022). "In a meta-analysis of 488 patients with chondrosarcoma, IDH1 and IDH2 mutations were detected in 39% and 12% of patients, respectively." (PMID 35163019, 2022). "IDH1/2 mutations are characteristic gene mutations that are detected in approximately 50% of chondrosarcomas and central and periosteal cartilaginous tumors." (PMID 35163019, 2022). "Nonetheless, herein, we identified a strong correlation between HIF-1α activation and IDH1 mutation status in chondrosarcoma cells." (PMID 35198082, 2022). "IDH mutations are observed in more than half of all cases of chondrosarcoma, and most of them are IDH1-related." (PMID 35408900, 2022). "This case report showed MS complicated by giant chondrosarcoma in the left ankle with an IDH1 R132C mutation, which is appropriate to monitor the development of MS pathology and other concomitant lesions." (PMID 35765075, 2022). "Significant enrichment with mutated IDH1 and 2 genes has been observed in chondrosarcoma (~50% cases)." (PMID 35055016, 2022). "In chondrosarcomas, Ollier disease, and Maffucci syndrome, a high incidence of IDH1 and IDH2 mutations has been reported." (PMID 35163019, 2022). "This is a case report of MS complicated by giant chondrosarcoma in the left ankle with an IDH1 R132C mutation." (PMID 35765075, 2022). "According to the primary diagnosis in this cohort, we also detected H3F3A in giant cell tumor of bone and malignant giant cell tumor of bone, IDH1/IDH2 mutations in chondrosarcoma, and NCOA2 fusion in mesenchymal chondrosarcoma." (PMID 35756627, 2022). "Examples include HEY1-NCOA2 in mesenchymal chondrosarcoma, IDH1/2 mutations in chondrosarcoma and TFCP2 rearrangements in rhabdomyosarcoma." (PMID 35875137, 2022).
chondrosarcoma (continued). "Consistently, in chondrosarcoma, the presence of IDH1 and 2 mutation associates with widespread deregulation of DNA methylome resulting in CIMP." (PMID 35055016, 2022). "Gain-of-function mutations of IDH1/2 are found in 38–70% of primary central chondrosarcomas and only lead to DNA hypermethylation." (PMID 34070455, 2021). "Isocitrate dehydrogenase (IDH1/2) mutations were found in 50% of central chondrosarcomas and are considered an early event." (PMID 34359724, 2021). "Additional studies are necessary to elucidate the prognostication of IDH1/2 mutations in chondrosarcomas of the head and neck." (PMID 34085407, 2021). "Several potential therapeutic targets in dedifferentiated chondrosarcoma have been identified, including IDH1/2 mutations in approximately half of the cases." (PMID 34359724, 2021). "In cranial chondrosarcomas, we demonstrated different patterns of IDH1/2 mutations by the anatomical site of neoplasms." (PMID 34085407, 2021). "38-79% of chondrosarcomas have IDH1/IDH2 mutations with an enzymatic neomorphic activity and they use NADPH or NADH as a cofactor." (PMID 34938658, 2021). "Post-natal IDH1 R172Q mutations in chondrocytes in mice leads to enchondromas, which is a precursor lesion for chondrosarcoma." (PMID 34938658, 2021). "Specifically, mutations in IDH1 or IDH2 isoforms are identified in approximately 60% of chondrosarcomas." (PMID 34938658, 2021). "We included studies providing IPD of chondrosarcoma with available IDH1/2 mutational status for meta‐analysis." (PMID 34085407, 2021). "Patients with chondrosarcoma carry more than 50% of IDH1/2 mutant heterozygotes, and IDH1 R132 is the most common mutation, followed by IDH2 R172." (PMID 33981605, 2021). "We also observed the same trend of correlation of IDH mutation and patient RFS in chondrosarcomas and a decreased risk of tumor relapse in patients harboring IDH1/2 mutations." (PMID 34085407, 2021). "IDH1 and 2 mutated chondrosarcoma cells have been shown to up-regulate glutaminolysis and glycolysis for the production of a-KG." (PMID 34938658, 2021). "This meta‐analysis aims to explore the clinicopathological and prognostic characteristics of IDH1/2 mutations in chondrosarcoma." (PMID 34085407, 2021). "This switch has been reported in a four-case study, and in chondrosarcoma cells harboring the double mutations IDH1-R132G/IDH2-R172V and IDH1-R132H/IDH2-R172S." (PMID 34065551, 2021). "IDH1 mutations are found in ~50% of all chondrosarcoma patients and are involved in malignant transformation." (PMID 33076370, 2020). "Instead, in this study, we investigated the role of IDH mutation in chondrosarcoma by directly knocking out the mutant allele in two IDH1-mutant chondrosarcoma cell lines, JJ012 and HT1080." (PMID 31935911, 2020). "To study the function of IDH1 mutation in chondrosarcoma, we examined the effects of IDH1mut knockout on cell proliferation, cell migration, and anchorage-independent cell growth, in the genetically modified JJ012 and HT1080 cells." (PMID 31935911, 2020). "Recently, IDH1/2 mutations have been reported in enchondroma, as well as in conventional (central and periosteal) and dedifferentiated chondrosarcoma." (PMID 31935911, 2020). "Consistent with previous results, loss of IDH1mut in the KO chondrosarcoma cell lines failed to induce significant changes in cell proliferation, supporting the idea that IDH1 mutations are dispensable for chondrosarcoma cell proliferation." (PMID 31935911, 2020). "Thereby, the association between SOX9 and IDH1 highlight the crucial role of SOX9 in chondrosarcoma biology." (PMID 33076370, 2020). "Overall, mutations in IDH1/IDH2 or EXT1/EXT2 have been shown to have a role in the pathogenesis of most common central or peripheral chondrosarcomas, respectively." (PMID 32295254, 2020). "Regardless, our cell line panel provides a unique model to functionally study the role of IDH1 mutation in chondrosarcoma." (PMID 31935911, 2020).
chondrosarcoma (continued). "Two chondrosarcomas reported as secondary to osteochondroma, peripheral subtype, were reclassified as central following detection of somatic IDH1/2 variants." (PMID 32573957, 2020). "The IDH1 variant occurred at amino acid 132 in the IDH1 gene in two sarcoma cases; chondrosarcoma R132C and pleiomorphic sarcoma R132G substitution respectively." (PMID 32570879, 2020). "For patients with active disease, it was disappointing that only a single clinical trial was open to the recruitment of patients with sarcoma and that this was limited to surgically untreatable chondrosarcomas with somatic IDH1 mutations." (PMID 32573957, 2020). "In chondrosarcoma cell lines, CB-839 activity correlated with the status of isocitrate dehydrogenase 1/2 (IDH1/2), as the cells carrying IDH1/2 mutation were more susceptible to this compound than the wild type cells." (PMID 32880874, 2020). "The data reported here demonstrate that ivosidenib has a favorable PK profile in patients with IDH1-mutated solid tumors, with robust suppression of plasma 2-HG in patients with cholangiocarcinoma or chondrosarcoma." (PMID 31028664, 2020). "Eighty-seven percent of the solitary and multiple enchondromas, ~ 50% of the primary central conventional chondrosarcomas and 86% of the secondary central chondrosarcomas harbour heterozygous point mutations in IDH1 and IDH2." (PMID 31728625, 2020). "Herein, we sought to analyze the role of IDH1 mutation in chondrosarcoma tumorigenesis by knockout of the IDH1mut." (PMID 31935911, 2020). "Mutations in isocitrate dehydrogenase enzymes (IDH1/2) were recently described in several cancers, including conventional and dedifferentiated chondrosarcomas." (PMID 31935911, 2020). "AGI-5198 also reduced 2-HG levels in human chondrosarcoma cells that harbor IDH1/R132G and IDH1/R132C mutations in a dose-dependent manner." (PMID 30857299, 2019). "Central chondrosarcomas carry mutations in the genes encoding the enzymes isocitrate dehydrogenase 1 or -2 (IDH1 or IDH2) in approximately 50% of cases, resulting in production of the oncometabolite d-2-hydroxyglutarate (D-2HG)." (PMID 31160965, 2019). "Sequencing analysis of common mutations in chondrosarcoma identified point mutations in IDH1 (p.R132L) in CDS01 cells and IDH2 (p.R172G) in CDS17 and T-CDS17 cells which were also detected in the corresponding patient tumor samples." (PMID 30987403, 2019). "Central conventional chondrosarcomas harbor specific point mutations in isocitrate dehydrogenase 1 or -2 (IDH1 or IDH2) in ~50% of the cases." (PMID 31810230, 2019). "Chondrosarcomas are chemo- and radiotherapy resistant and frequently harbor mutations in isocitrate dehydrogenase (IDH1 or IDH2), causing increased levels of D-2-hydroxyglutarate (D-2-HG)." (PMID 31810230, 2019). "Mutations in IDH1/2, present in over half of primary conventional chondrosarcomas, render the development of IDH inhibitors a promising treatment option." (PMID 30586948, 2018). "Our results indicate that there is limited preclinical rationale to select chondrosarcoma patients for treatment with these compounds based on their IDH1/2 mutation status." (PMID 29576625, 2018). "Chondrosarcoma is a malignant cartilage-forming bone tumour in which mutations in IDH1 and IDH2 frequently occur." (PMID 29576625, 2018). "This is consistent with chondrosarcoma abnormalities, specifically mutations in either IDH1 (cytosolic) or IDH2 (mitochondrial)." (PMID 28056047, 2017). "Heterozygous mutations in the IDH1 isoform are particularly common in gliomas, chondrosarcomas and some leukemias." (PMID 27324272, 2016). "Mutations in isocitrate dehydrogenase enzymes (IDH1/2) were recently described in several cancers including chondrosarcomas." (PMID 26368816, 2015).